CD4 (CD4 molecule)
Diseases named in the same sentence as CD4 in open-access papers (continued):
Sharing a sentence is not in itself a finding about the gene and the disease.
colitis (continued). "Furthermore, the CTX was able to down-modulate ILC3 and Th17 immune response and to induce the secretion of anti-inflammatory mediators and CD4+Foxp3+ cells in mice with TNBS-induced colitis." (PMID 25853847, 2015). "Indeed, adoptively transferred Foxp3+CD4 Treg cells were able to suppress the disease development in murine models of colitis, arthritis, and experimental autoimmune encephalitis." (PMID 25759842, 2015). "Thus, the relative incapability of the expanded cells to stimulate T cells should allow them to exert better protection against colitis induced by CD4+ CD25− T cells than conventional DCs." (PMID 26024301, 2015). "Therefore, the aim of this study was to investigate the contribution of HQT to the amelioration of colitis and CD4+ T cells immune homeostasis in 2,4,6-trinitrobenzenesulfonic acid- (TNBS-) induced acute colitis." (PMID 26347453, 2015). "Co-injection with WT tTregs effectively repressed the induction of colitis by CD4+CD25− T cells." (PMID 25695215, 2015). "Interestingly, elevated levels of cell-surface B272 reached a threshold between 15 to 23 weeks and correlated with the stabilization of pro-inflammatory CD4+ T-cells expansion and with colitis severity." (PMID 26125554, 2015). "Interestingly, CD8+CD122+ and CD4+CD25+ Tregs cooperatively suppressed colitis mediated by CD4+ T-cells, whereas the systemic lupus erythematosus-like disease in B6-Yaa mutant mice was associated with a defect in CD8+CD122+ T-cells." (PMID 26539191, 2015). "Indeed, antibody-mediated CD4-depletion in vivo prevented colitis in these mice corroborating the importance of CD4+ T cells in the pathogenesis." (PMID 25944983, 2015). "Thus, it is noteworthy that butyrate induces the differentiation of regulatory T cells in vitro and in vivo, and ameliorated the development of colitis induced by adoptive transfer of CD4(+) CD45RB(hi) T cells in Rag1(−/−) mice." (PMID 25920452, 2015). "Consistent with normal levels of Foxp3 in the recovered Tregs, Hif1a-knockout re-established the ability of Dtx1−/− tTregs to repress CD4+CD25− T cell-induced colitis in Rag1−/− mice as determined by colitis score readout, body weight loss and intestinal morphology." (PMID 25695215, 2015). "Transfer of BM memory CD4+ T cells into new recipient SCID mice reproduced colitis." (PMID 26734007, 2015). "It is therefore conceivable that the protective effect of HQT on TNBS-induced colitis might be explained by its capability to induce Treg cells and rebalance CD4+ T cell subsets." (PMID 26347453, 2015). "In addition, co-transfer of VDR KO CD8+ T cells with naïve CD4+ T cells accelerated colitis development." (PMID 24502291, 2014). "Finally, IL-6 has been identified in several cell types within tumors of mice with colitis-induced cancer including epithelial cells, CD4+ cells, and monocytes." (PMID 25478789, 2014). "Our findings suggest that the reduction of Flt3 and Flt3L expression may possibly induce colonic immunoregulatory imbalance between CD103+MHCII+DCs and CD4+CD25+FoxP3+T-regs in DSS-induced colitis." (PMID 25371672, 2014). "Coinjection of CD4+CD45RBlo cells (activated/memory T cells) could prevent the development of colitis." (PMID 24728142, 2014). "Mice lacking MHCII selectively on ILCs3 exhibit increased frequencies of proliferating CD4+ T cells in the blood, significant increase in commensal bacteria-specific serum IgG, and development of colitis characterized by enhanced production of IFN-γ, IL-17A, and TNF by mucosal CD4+ T cells." (PMID 25061260, 2014). "On the other hand, FACS-purified Tregs derived from β2i/MECL-1&β5i/LMP7-deficient, immunocompetent mice suppress CD4+ T-cell-induced colitis upon cotransfer (not shown), indicating that β2i/MECL-1&β5i/LMP7-deficiency does not disable Treg function." (PMID 24740379, 2014). "In addition, there was much higher level of CD4+CD25+Foxp3+ Tregs in ERC treated mice than that of untreated colitis mice and normal mice (*p < 0.01)." (PMID 25475342, 2014).
colitis (continued). "Similarly, our results demonstrated that CD4+CD25+Foxp3+ Tregs decreased significantly in the untreated colitis mice as compared to that of normal mice." (PMID 25475342, 2014). "Adoptive transfer of CD4+CD45RBhi T cells (naive T cells) from healthy wild-type to lymphopenic mice leads to colitis and small bowel inflammation at 5–8 weeks following T cell transfer which represents an important model to study specific T cells involvement in dysregulation." (PMID 24728142, 2014). "Taken together, these results indicate that MHCII expression by IECs attenuates bacterial-driven colitis by preventing exacerbated effector Th1 cell accumulation and the establishment of an unfavourably altered ratio between conventional CD4+ T cells and FoxP3+ Treg cells." (PMID 24489792, 2014). "Transfer of Treg cell–depleted CD4+ CD45RBlow cells into Rag−/− mice could also induce colitis, but with a slower onset than with CD4+ CD45RBhigh T cells." (PMID 25133396, 2014). "The aim of this study was to investigate whether central activation of the CAP alters the function of dendritic cells (DCs) and sequential CD4+/CD25−T cell activation in the context of experimental colitis." (PMID 25295619, 2014). "Curative treatment of chronic colitis with SmSWP reduced the severity of colitis induced by the adoptive transfer of CD4+CD25−CD62L+ T cells in immunocompromised SCID mice, as shown by a significant improvement of all inflammatory parameters studied, except one." (PMID 25313594, 2014). "IL-6Rα-deficient CD4+ CD45RBhi T cells failed to induce colitis when transferred into RAG2 KO mice and compared to WT mice, IL-6RαT-KO mice were also resistant to the induction of EAE following immunization with MOG35-55/CFA." (PMID 24842874, 2014). "In vitro culture of naïve T cells with nicotine enhances the effect of cell activation-induced expression of FoxP3, and nicotine treatment markedly increases the influx of CD4+CD25+FoxP3+ T regulatory cells (Treg) into the gut in rodent oxalazone-induced colitis." (PMID 25110981, 2014). "A more complex scenario emerged however from studies in chronic CD45RB (high) CD4+ T cell transfer and anti-CD40 antibody-induced acute innate colitis models in Rag1-deficient mice showing that IL-23R signaling in ILCs3 is protective in the former and pathogenic in the latter." (PMID 25061260, 2014). "The anti-colitis effect of L. salivarius 33 was correlated with the expansion of CD4+Foxp3+ T cells in the MLN while VSL#3 increased the population of Tregs bearing surface TGF-beta in the form of latency-associated protein (LAP) (LAP+ T cells) in the lamina propria." (PMID 24465791, 2014). "In addition, co-transfer of VDR KO CD8+ T cells with naïve WT CD4+ cells accelerated the development of colitis in Rag KO recipients." (PMID 24502291, 2014). "In conclusion, the reduction of Flt3 and Flt3L expression may possibly induce colonic immunoregulatory imbalance between CD103+MHCII+DCs and CD4+CD25+FoxP3+T-regs in DSS-induced colitis." (PMID 25371672, 2014). "In T-cell transfer-induced colitis, inflammation is mediated by activated CD4+ T-cells." (PMID 24740379, 2014). "Furthermore, this effect corresponded to the expansion of Tregs and the colitis suppressive effect of LZ-8-stimulated CD4+ T cells." (PMID 23864893, 2013). "The ligand for CD69 has not been identified, but it is possible that the anti-CD69 mAb may block the interaction between CD69 and putative CD69 ligands, resulting in reduced CD4 T cell migration and attenuated colitis." (PMID 23785429, 2013). "In addition, the deficiency of PPARγ in nTreg cells impairs their ability to prevent effector T cell-induced colitis following transfer of naïve CD4+ T cells into SCID recipients." (PMID 23592971, 2013). "In murine colitis models, IL-17A production from CD4+ T cells is protective because IL-17A directly suppresses the development of colitogenic Th1 cells via IL-17R expressed on activated CD4+ T cells." (PMID 23383714, 2013).
colitis (continued). "In addition to the enhanced frequencies of P-lig+ CD4+ T cells we observed a dramatic increase in the frequency of α4β7 CD4+ T cells in the colitis mice indicating indirectly that the majority of effector cells had been exposed to RA during priming." (PMID 23630623, 2013). "However, as we observed a strong increase in the frequency of α4β7 CD4+ cells during colitis this effect seems to be negligible in vivo." (PMID 23630623, 2013). "Adoptive transfer of TR2-deficient CD4+ T cells into lymphopenic hosts led only to colitis but not systemic disease." (PMID 24115907, 2013). "Similarly, the development of colitis in mice transferred with CD4+ T cells depleted of regulatory T cells confirms the functional importance of this subset in restraining cells which are otherwise capable of driving inflammatory disease 22–24." (PMID 23405904, 2013). "However, during experimental colitis enhanced frequencies of P-lig expressing CD4+ T cells were reported within intestinal sites, such as the MLN and the lamina propria." (PMID 23630623, 2013). "In this model, colitis was induced by transplanting RAG KO mice with CD45RBhigh CD4 T cells." (PMID 23785429, 2013). "In conclusion, the data presented here indicate that the CD4+ T cell intrinsic expression of functional Nod2 is capable of modulating T cell signalling yet Nod2 is dispensable for the T cell induction and regulation of colitis and for both the development and the function of CD4+ Treg cells." (PMID 24324812, 2013). "Moreover, a study of antigen specificity of CD4+ T cells isolated from SCID mice suffering from colitis after transfer of naïve T cells showed that these cells were highly reactive to fecal extracts and are Th1 skewed." (PMID 23936123, 2013). "Although Nod2 deletion in CD4+ T cells has been shown to impair the induction of colitis in the murine T cell transfer model, the analysis of T cell intrinsic Nod2 function in T cell differentiation and T cell-mediated immunity is inconsistent between several studies." (PMID 24324812, 2013). "Although activation of NF-kB plays a pivotal role in the activation, differentiation and proliferation of T cells, we observed that transfer of Nod2 deficient naive CD4+CD45RBhigh T cells in Rag1-/- mice did not impair the induction of colitis." (PMID 24324812, 2013). "As it has not been previously published if antigen-specific T cells develop in mice experiencing DSS colitis, our aim was to investigate if CD4+ T cells directed against oral antigens could be found after the resolution of colitis." (PMID 23936123, 2013). "In the colitis model, effector CD4 T cell survival required the presence of HVEM-BTLA cis-complex." (PMID 24205056, 2013). "Colitis progression culminates with the reduction of CD4+LAP+ regulatory T cells in the intestine." (PMID 22400037, 2012). "As an alternative to chemically induced colitis, several models helped to gain valuable insight into the underlying pathology of IBD, such as the model based on transfer of CD45RBHi CD4+ T cell to immunodeficient recipients or the development of colitis in IL-10 deficient mice." (PMID 23226271, 2012). "Thus, bortezomib treatment attenuated DSS-induced colitis by inhibiting excessive IFN-γ production from CD4+ and CD8+ T cells." (PMID 22479648, 2012). "Notably, protection from colitis by cotransfer of regulatory T cells (Treg cells), which are enriched among CD4+ T cells in the BM, prevented the HSC expansion." (PMID 23200826, 2012). "However, mice with severe colitis showed significantly reduced numbers of both CD4 and CD8 SP thymocytes compared to the littermate controls." (PMID 22590596, 2012). "It is possible that IL-7R expression by cells other than CD4+ T cells has a modest effect in their model as they noted a trend of increased colitis scores in IL7R−/− x Rag2−/− recipients of wildtype naïve T cells compared to Rag2−/− -only recipients, although these differences were not significant." (PMID 23057802, 2012).
colitis (continued). "Thus, the hyperplastic mucosa in established colitis was heavily infiltrated by a ten-fold increase in CD4+ T cells, and the proportion of FoxP3+ cells rose by two- to three-fold." (PMID 21966415, 2011). "Like naïve CD4+ cells lacking RORγt, CD4+ T cells deficient in Th1-related transcription factors (that is, Stat4 and T-bet) are unable to induce colitis when transferred to recipient mice." (PMID 22082127, 2011). "Additionally, we compared the ability of wildtype C57BL/6 or HVEM-/- and LIGHT-/- CD4+CD45RBhigh T cells to mediate experimental colitis following their transfer into immuno-compromised RAG1-/- hosts." (PMID 21533159, 2011). "In this study, we address the hypothesis that colitis in Gαi2−/− mice is a consequence of a qualitative or quantitative defect in CD4+FoxP3+ regulatory T cells (Treg)." (PMID 21966415, 2011). "In addition to the CLS, the increase in activated CD4+ T cells in colitis + HFD mice leads to increased MCP-1/CCL2 release in this tissue, which induces migration and activation of macrophages that originate from the CLS and enhance inflammation." (PMID 22073943, 2011). "The development of colitis in the Gαi2−/− mouse model is dependent on the presence of an enteric microflora (unpublished observations) and is characterized by a Th1 CD4+ T cell response, with increased production of IFN-γ, together with increased levels of IL-1, IL-6 and TNF-α in inflamed tissue." (PMID 21966415, 2011). "However, we found that B6 WT CD4+CD25+Foxp3+ Treg efficiently suppressed T-cell-mediated colitis in both B6.RAG−/− or B6.RAG−/−.TLR2−/− recipients." (PMID 19950179, 2010). "CD4+CD25+ Treg cells are known to inhibit colitis and maintain intestinal homeostasis." (PMID 20399121, 2010). "To assess the role of IL-23R expression on T cells in the development of colitis, we transferred CD4+CD45RBhi cells isolated from wild-type (WT) or Il23r−/− mice into B and T cell-deficient Rag1−/− mice, with the latter allowing us to restrict IL-23 responsiveness to the innate immune compartment." (PMID 20732640, 2010). "Notably, IL-17A+IFN-γ+ CD4+ T cells are prominent in T cell-dependent colitis models and have also been recovered from the intestinal lesions of human CD patients." (PMID 20732640, 2010). "Furthermore, co-transfer of CD4+CD25+ Treg isolated from B6.TLR2–/– mice inhibited colitis development to a similar degree as B6 WT CD4+CD25+ Treg." (PMID 19950179, 2010). "During acute DSS-colitis, mice receiving vehicle showed a significant drop in total percentage of CD4+CD25+FoxP3+ splenocytes, while mice receiving cis-UCA maintained pre-DSS levels of CD4+CD25+FoxP3+ cells and were significantly higher than PBS control levels." (PMID 21060867, 2010). "Moreover, mice that were monoassociated with H. muridarum displayed an accelerated development of IBD-like lesions in a CD45RBhigh CD4+ T cell transfer model of experimental colitis." (PMID 19401779, 2009). "Because IL-23 promotes IL-17 production by CD4+ T cells, we reasoned that colitis might be dependent on T cell-derived IL-17." (PMID 18400195, 2008). "The content of IL-10 in culture supernatant was measured by an enzyme-linked immunosorbent assay (ELISA), and CD4+Foxp3+ Treg cells were sorted and adoptively transferred (40,000 cells/mouse) via tail vein injection into C57BL/6 J mice, followed by DSS administration to induce acute colitis." (PMID 40597393, 2025). "Additionally, it is noteworthy that ATG7 is up‐regulated in A‐CD patients and experimental colitis mouse models, predominantly expressed in pro‐inflammatory CD4+IFNγ+ T cells, indicating that ATG7 affects the CD4+ T cells differentiation in the process of inflammation." (PMID 40887825, 2025). "Based on previous findings demonstrating a correlation between the degree of homeostatic proliferation of CD4+ T cells and severity of colitis, we hypothesized that enhanced homeostatic proliferation of Cars2+/- naive CD4+ T cells can exacerbate colitis in certain circumstances." (PMID 40303402, 2025).
colitis (continued). "However, co-transferring CD4+ T cells inhibits colitis, indicating their crucial regulatory role." (PMID 38543070, 2024). "Interestingly, in the transfer of naïve T cells, IL‐22 from innate (NK/ILC) cells was suggested to next to the IL‐22 derived from CD4+ cells, also plays a protective role, since performing the transfer in Rag1−/−Il22−/− double KO mice resulted in exacerbated colitis." (PMID 38363052, 2024). "Our previous studies showed that a novel forkhead box protein P3 (Foxp3) negative Tregs (Treg-of-B cells), induced by culturing naïve CD4+ T cells with B cells, could protect against colitis and downregulate T helper (Th) 1 and Th17 cell cytokines in T cell-mediated colitis." (PMID 39085655, 2024). "Importantly, APS reversed the expression changes in the TIGIT molecule on mTh17/mTreg cells in the colitis mice with fewer CD4+CCR6+TIGIT+, CD4+CCR7−CCR6+TIGIT+ and CD4+CCR7−CCR6+TIGIT+ cells and more CD4+Foxp3+TIGIT+, CD4+CCR7−Foxp3+TIGIT+ and CD4+CCR7−Foxp3+TIGIT+ cells." (PMID 38202824, 2024). "To determine whether the 83 kb Il2 enhancer contributes to auto-inflammatory disease susceptibility in vivo, we used an adoptive transfer model of IBD in which the development of colitis is determined by the balance between conventional and regulatory CD4+ T cell activities." (PMID 39302339, 2024). "In addition, due to the damage of Treg differentiation, the conditional knockout of JunB in mouse CD4+ T cell is more susceptible to colitis induced by dextran sulfate sodium (DSS), and deficiency of JunB in vitro CD4+ T cells resulted in the failure of IL-2-induced Treg cell differentiation." (PMID 37731821, 2023). "Treatment with tofacitinib immediately after CD4+ transfer resulted in an enhanced expansion of inflammatory CD4+ T cells and did not prevent occurrence of colitis, however, treatment after start of symptoms of colitis ameliorated disease activity on a clinical basis and histological analyses." (PMID 36882462, 2023). "Hence, GPR15 is capable of directing the colon homing of both Treg and Teff CD4+ T cells in mice, and the impact of this receptor in colitis pathology will depend on the experimental settings regarding the relative requirement of Treg and Teff subsets for the development of colitis." (PMID 37457732, 2023). "In contrast to the direct in vitro suppression of IL-10 expression by tofacitinib, however, the number of IL-10+ CD4+ T cells in colitis mice on day 90 could not only be reverted by the late administration of tofacitinib but also sometimes even exceeded the levels observed in control mice." (PMID 37275854, 2023). "CD4-neighbouring SIGLEC8 RNA molecules were also significantly associated with NF-κB (NFKB1) and IFNγ (IFNGR1, STAT1 and IRF1) signalling components, which indicates that the same pathways might drive interactions between A-Eos and CD4+ T cells in mouse and human colitis." (PMID 36509106, 2023). "Thus, TRPA1 in CD4+ T-cells appears to reduce the severity of T-cell-mediated colitis." (PMID 37039840, 2023). "Notably, targeting IL23 did not completely prevent colitis, probably because pathogenic cytokine production was only reduced in CD4+ T cells, but not CD8+ T cells." (PMID 37872166, 2023). "Consistently, the absolute numbers of these CD4+ T lymphocyte subsets also revealed corresponding tendencies after gut microbiota depletion, indicating that the presence of gut microbiota was indispensable for the protective effects of HUMSCs on the intestinal immune homeostasis in colitis." (PMID 37749611, 2023). "In addition to being implicated in colitis, CD4+Th17 cells have been shown to depend on STAT3 for their normal development." (PMID 37296943, 2023). "However, based on these previous studies, the role of DN iNKT cells in balancing the ratio of Foxp3+CD25+ Treg cells to Foxp3−CD25+CD4+ T cells during the pathogenesis of colitis remains largely unknown." (PMID 36499642, 2022).